MIF (macrophage migration inhibitory factor)
Diseases named in the same sentence as MIF in open-access papers (continued):
Sharing a sentence is not in itself a finding about the gene and the disease.
colitis (32 papers, 2009 to 2025). Inflammation of the colon. "Previously, we described a dual role for MIF in CRC using the colitis-associated AOM/DSS mouse model." (PMID 40835826, 2025). "We found both predictive and diagnostic value of MIF with fatigue and of eotaxin with both colitis and pneumonitis." (PMID 39687621, 2024). "Validation in larger cohorts would be of interest, particularly for associations like MIF with fatigue, eotaxin with colitis and pneumonitis, MIG with endocrine inflammation, and MIG and IP-10 with dermatitis." (PMID 39687621, 2024). "We demonstrated that MIF is specifically elevated in tumor cells and drives tumor growth in this acute colitis-associated (‘sporadic’) CRC model." (PMID 33542244, 2021). "Inhibition or loss of MIF protects mice from chemically induced colitis, while transgenic MIF expression exacerbates colitic conditions." (PMID 26352431, 2015). "In summary, MIF supports tumor growth in an acute colitis-associated CRC mouse model." (PMID 33542244, 2021). "Similarly, transgenic mice that overexpress MIF are more susceptible to DSS-induced colitis." (PMID 26183215, 2015). "The chronic HIF stimulation in the colon epithelial cells initiates a hyperinflammatory reaction and, at least in mice, HIF-1α enhances experimental colitis through a MIF-dependent inflammatory signaling cascade, reversed by MIF inhibition." (PMID 34692718, 2021). "Mechanistically, MIF, which also is increased in colitis, stimulated the CD74 receptor, activating pro-proliferative Akt and ERK pathways." (PMID 32655566, 2020). "Namely, MIF is highly expressed in the colon of mice and it probably mediates colitis development through the stimulation of macrophage infiltration in the colon." (PMID 29679061, 2018). "MIF has been found to play a role in a mouse model of experimentally induced colitis, and MIF plasma concentrations are increased in individuals with Crohn's disease." (PMID 26183215, 2015). "Shah and colleagues have reported that HIF expression exacerbates colitis through a MIF-dependent mechanism." (PMID 26183215, 2015). "MIF is a crucial mediator of HIF-induced pro-inflammatory responses in a mouse model of experimentally induced colitis." (PMID 26183215, 2015). "In contrast, the oral FSG treatment significantly decreased MIF expression 24 h after colitis (p<0.05) and IL-1β levels on days 1 and 3 post-TNBS (p<0.05; p<0.01 respectively) compared to corresponding values obtained in colitic rats." (PMID 23166707, 2012). "MIF has previously been decribed in many other proinflammatory diseases such as arthritis, septic shock, colitis and hypersensitivity syndrome." (PMID 22693633, 2012). "In this model, neutralization of MIF with an anti-MIF polyclonal antibody suppressed the disease activity of colitis, suppressing the production of Th1-type cytokines and MMP-13 in the colon." (PMID 23050964, 2012). "In this context, it is conceivable that the DSS-induced colitis model is appropriate for investigation of the effectiveness of the antisense MIF/SPG complex in the treatment of colitis." (PMID 23050964, 2012). "Our study shows that FSG treatment prevented the colitis-induced increase in IL-1β and MIF in the rat colon." (PMID 23166707, 2012). "In this report, we have provided an overview of the molecular characteristics and biological aspects of MIF, particularly with respect to colitis, and discussed therapeutic approaches for targeting MIF for IBD." (PMID 23050964, 2012). "Several studies report that estrogens have anti-inflammatory activity in colitis, partly occurring through ER-dependent down-regulation of MIF production by epithelial cells and macrophages." (PMID 23166707, 2012). "The administration of the antisense MIF/SPG complex led to significant protection against DSS-induced colitis, as evaluated by clinical signs and histopathological markers, including weight loss and colon shortening." (PMID 23050964, 2012).
colitis (continued). "MIF isolated from A. simplex increased Treg responses and reduced colitis severity." (PMID 33343521, 2020). "We investigated the expression of the CD74 ligand MIF in colitis." (PMID 32004754, 2020). "Furthermore, in our results, the significant association of MIF polymorphisms with CIHM of CDKN2A were found in chronic continuous of clinical type and total colitis phenotype." (PMID 33046033, 2020). "This study was conducted to determine colitis-associated CRC development in the absence of systemic MIF." (PMID 31360118, 2019). "MIF-knockout (MIF−/−) or wild-type (WT) mice treated with anti-MIF therapy did not develop ulcerative colitis, or ulcerative colitis was significantly reduced in these mice, while transgenic mice that overexpressed MIF developed more severe colitis." (PMID 31360118, 2019). "The rAs-MIF appears to ameliorate dextran sodiumsulphate-induced colitis, suggesting that MIF might be useful as a therapeutic agent for the treatment of intestinal inflammatory disease." (PMID 28402951, 2017). "In experimental colitis, MIF-deficient mice failed to develop disease, but reconstitution of MIF-deficient mice with wild-type innate immune cells restored colitis." (PMID 25821795, 2015). "Thus continuous MIF production by the innate immune system is critical for murine colitis development." (PMID 25821795, 2015). "Conversely, antibodies against MIF ameliorate DSS-induced colitis in mice." (PMID 26183215, 2015). "The administration of the antisense MIF/SPG complex significantly ameliorated colitis by suppressing MIF production without causing any adverse effects in a mouse model." (PMID 23050964, 2012). "We demonstrated that the expression of MIF was increased in DSS-induced colitis in mice." (PMID 23050964, 2012). "In all of these cases, few or no histological features of colitis were observed in MIF-deficient mice, and infiltration of neutrophils and macrophages was much less frequent." (PMID 23050964, 2012). "Since both MIF and IL-1β induce neutrophil recruitement, and that blockade of MIF activity down-regulates IL-1β, it is likely that the decrease of neutrophil influx and IL-1β release in the inflamed areas would result from FSG-mediated inhibition of MIF production in the acute phase of colitis." (PMID 23166707, 2012). "Considering these findings together, we hypothesize that MIF stimulates the accumulation of innate immune cells such as neutrophils and macrophages in the colon of mice with colitis." (PMID 23050964, 2012). "This difference may be related to the anti-inflammatory effect of oestrogen, study found that oestrogen decreased the production of macrophage migration inhibitory factor, which affected the susceptibility to inflammation in the colon by reducing the TNF-α and IL-1β production in colitis." (PMID 37907907, 2023). "In addition, MIF is also a target of sex steroids in some inflammatory models; progesterone increases MIF production in the female rat colon in experimental colitis, which may be another reasonable hypothetical triangulation during placental development." (PMID 20684790, 2010). "In female rats, estrogen and progesterone reduced the production of macrophage migration inhibitory factor (MIF), which promotes tumor necrosis factor (TNF)-alpha and interleukin-1β (IL-1β) expression in early colitis." (PMID 40636118, 2025). "The phenotype named Colitis contains seven DEGs from our lists: IL10, IL11, IL1B, IL1RN, IL6, MIF and TNF." (PMID 34680872, 2021). "Here, mice treated with rAs-MIF regained previously lost weight and had lower disease activity indices in DSS-induced colitis." (PMID 33343521, 2020). "In addition, established colitis could be treated with anti-MIF immunoglobulins." (PMID 25821795, 2015).
colitis (continued). "Serum MIF levels were found to be significantly higher in patients with UC than in normal controls, and another study suggest that immunization with helper T epitope DNA-vaccine targeting MIF may be a useful approach for the treatment of colitis including inflammatory bowel diseases." (PMID 23759989, 2013). "Pro-inflammatory cytokines like macrophage migration inhibitory factor (MIF), IL-1β and TNF-α predominate in inflammatory bowel diseases (IBD) and TNBS colitis." (PMID 23166707, 2012). "Furthermore, MIF’s classical receptor, CD74, which promotes cancer cell proliferation, is increasingly expressed during the transition from colitis to adenoma and carcinoma in human tissues." (PMID 40835826, 2025). "Given the importance of MIF in cancer and to determine whether MIF supports CRC tumorigenesis, we used the severe CRC AOM/DSS mouse model, which includes one phase of acute colitis." (PMID 33542244, 2021). "MIF was significantly over-expressed only 24 h after TNBS administration (p<0.05) while colonic levels of IL-1β were markedly increased at 24 h, 3 d and 5 d after TNBS-induced colitis (p<0.01)." (PMID 23166707, 2012). "Interestingly, the macrophage migration inhibitory factor (MIF) homolog from Anisakis simplex (As-MIF) has also been shown to induce upregulation of IL-10 in both lymph node and intestinal epithelial cells, and also increases Foxp3+ Treg expression in mice subject to DSS-induced colitis." (PMID 28302598, 2017).
inflammatory bowel disease (32 papers, 2012 to 2025). A spectrum of small and large bowel inflammatory diseases of unknown etiology. "In particular, studies using neutralizing antibodies or MIF deficient animals showed that inhibition of MIF can ameliorate disease development in animal models of inflammatory bowel disease and arthritis." (PMID 24349480, 2013). "The -173 G/C polymorphism in the macrophage migration inhibitory factor (MIF) gene has been implicated in susceptibility to inflammatory bowel disease (IBD), but the results are inconclusive." (PMID 23759989, 2013). "MIF is associated with various autoimmune diseases, such as rheumatoid arthritis, and inflammatory bowel disease (IBD)." (PMID 34575145, 2021). "Additionally, the genetic MIF-173G/C polymorphisms of MIF is associated with CRC stage progression, and has been linked to susceptibility and phenotype of inflammatory bowel diseases such as Crohn’s disease." (PMID 40835826, 2025). "Combined with CD74, MIF has been shown to promote wound healing in inflammatory bowel disease." (PMID 39974348, 2024). "In humans, increased MIF expression has been linked to pathogenesis in several inflammatory conditions including cystic fibrosis, atherosclerosis, asthma, nephrotic syndrome, inflammatory bowel disease (IBD), multiple sclerosis, rheumatoid arthritis, and systemic lupus erythematosus." (PMID 35215200, 2022). "The pharmacologic targeting of MIF has also been of great interest in a variety of inflammatory conditions including multiple sclerosis, systemic lupus erythrematosus, rheumatoid arthritis, inflammatory bowel disease, and other inflammatory disorders." (PMID 32625208, 2020). "Furthermore, we found that MIF increased the abundances of Proteobacteria, Deferribacteres, and Melainabacteria, suggesting that these bacteria may play an essential role in MIF treatment of inflammatory bowel disease." (PMID 34552579, 2021). "An array of in vitro and in vivo experiments has demonstrated that MIF is profoundly involved in the pathogenesis of acute and chronic inflammatory disorders, such as inflammatory bowel disease (IBD)." (PMID 23050964, 2012). "Gene expression of cluster of differentiation 74 (CD74), the receptor for cytokine macrophage migration inhibitory factor, is increased in patients with inflammatory bowel disease (IBD), however, the role of CD74 signaling in intestinal inflammation remains poorly understood." (PMID 32004754, 2020). "BTZO-1 and its active derivatives bound to MIF and protected cells and organs from oxidative insults via ARE activation in animal models with oxidative stress such as ischemia/reperfusion injury, inflammatory bowel diseases, and septic shock." (PMID 28191280, 2017). "On the other hand, a meta-analysis has shown that 173 polymorphisms are a risk factor for inflammatory bowel disease; however, due to a lack of clinical details and original data, the effect of MIF polymorphisms on disease progression and severity could not be analyzed." (PMID 27014277, 2016).
pancreatic ductal adenocarcinoma (32 papers, 2015 to 2025). An infiltrating adenocarcinoma that arises from the epithelial cells of the pancreas. "It had been reported that overexpression of MIF promoted tumor metastasis and was notably associated with poor prognosis of pancreatic ductal adenocarcinoma." (PMID 35619896, 2022). "Pancreatic ductal adenocarcinoma (PDAC)-derived exosomes enriched in macrophage migration inhibitory factor (MIF) promote activation of hepatic stellate cells (HSCs) and ECM remodeling via inducing TGF- β secretion in Kupffer cells." (PMID 38741166, 2024). "It has been found that macrophage migration inhibitory factor (MIF) existing in EVs derived from pancreatic ductal adenocarcinoma (PDAC) formed a pre-metastatic niche in the liver thus advancing liver metastasis." (PMID 36405712, 2022). "Liver Kupfer cells uptake pancreatic ductal adenocarcinoma exosomes containing macrophage migration inhibitory factor (MIF), thus leading to secretion of transforming growth factor beta (TGF-β)." (PMID 33451077, 2021). "In 2015, they further revealed that pancreatic ductal adenocarcinomas-derived exosomal macrophage migration inhibitory factor (MIF) was uptaken by mouse Kupffer cells." (PMID 34595207, 2021). "Downregulation of MIF in tumour‐derived EVs abolishes initiation of liver pre‐metastatic modulation and levels of MIF in EVs from pancreatic ductal adenocarcinoma patients are useful for early metastasis detection." (PMID 33145869, 2021). "Exosomal MIF levels are significantly higher in the stage I pancreatic ductal adenocarcinoma patients who eventually develop liver metastasis." (PMID 33170151, 2020). "In pancreatic ductal adenocarcinomas (PDACs), macrophage migration inhibitory factor (MIF) was found to be overexpressed in PDAC-derived exosomes, and its blockade impeded liver pre-metastatic niche formation." (PMID 29197379, 2017). "Macrophage migration inhibitory factor (MIF) is highly expressed in pancreatic ductal adenocarcinomas (PDACs)-derived exosomes and primes the liver for metastasis." (PMID 26985909, 2016). "Liver pre-metastatic niche formation was shown to be induced from pancreatic ductal adenocarcinomas (PDAC) derived exosomes that expressed high levels of macrophage migration inhibitory factor (MIF) and led to a fibrotic-microenvironment." (PMID 27088079, 2015). "Another group demonstrated that macrophage migration inhibitory factor, or MIF, was significantly expressed in EVs formed from pancreatic ductal adenocarcinomas (PDAC), and that blocking MIF inhibited the establishment of a pre-metastatic niche in the liver as well as metastasis." (PMID 36059497, 2022). "Furthermore, several reports have demonstrated that MIF cooperates with D-DT in pancreatic ductal adenocarcinoma, cervical cancer, and non-small cell lung carcinoma." (PMID 35091838, 2022). "Moreover, macrophage migration inhibitory factor (MIF) was found to be highly expressed in pancreatic ductal adenocarcinoma cell-derived sEVs, and its blockade prevented liver PMN formation and metastasis." (PMID 34646366, 2021). "Additionally, in pancreatic ductal adenocarcinoma, MIF was found to prompt the transition from epithelial phenotype to mesenchymal state of cancer cells." (PMID 34157052, 2021). "Exosomal macrophage migration inhibitory factor from pancreatic ductal adenocarcinoma cells (PDAC) contributes to pre-metastatic niche formation in the liver and may be used for diagnosis of PDAC liver metastasis." (PMID 30568162, 2018). "In terms of establishing whether MIF functions via EVs transport, Costa-Silva and colleagues reported that MIF is highly expressed in pancreatic ductal adenocarcinoma (PDAC)-derived EVs and its blockade prevents liver pre-metastatic niche formation and metastasis." (PMID 35842634, 2022).
pancreatic ductal adenocarcinoma (continued). "Besides, a study also showed that pancreatic ductal adenocarcinoma (PDAC)-derived exosomes containing macrophage migration inhibitory factor (MIF) were taken up by KCs and subsequently activated resident HSC via TGF-β, leading to upregulation of fibronectin (in space of disse)." (PMID 34067719, 2021). "For example, pancreatic ductal adenocarcinoma patients who developed liver metastasis produce tumor-derived exosomes carrying high macrophage migration inhibitory factor (MIF), which could induce liver pre-metastatic niche formation and subsequently enlarge liver metastatic burden." (PMID 34268118, 2021). "In pancreatic ductal adenocarcinoma (PDAC), exosome-derived protein macrophage migration inhibitory factor (MIF) enhances metastasis of the liver by promoting the development of the hepatic pre-metastatic niche." (PMID 37384249, 2023). "In patients with pancreatic ductal adenocarcinoma (PDAC), the amount of the protein MIF inside T-EVs may represent a prognostic marker for liver metastasis." (PMID 33081785, 2020).